LDHA (lactate dehydrogenase A)
Diseases named in the same sentence as LDHA in open-access papers (continued):
Sharing a sentence is not in itself a finding about the gene and the disease.
cancer (continued). "Further, we focused on the function of LDHA in cancer bio‐characteristics." (PMID 30403008, 2018). "Previous studies found that phosphorylation of LDHA and PDHK1 by FGFR1 was common in diverse cancers which could activate LDHA and PDHK1 and promote glycolysis." (PMID 29132384, 2017). "Lactate dehydrogenase A (LDHA) is overexpressed in various cancers." (PMID 28978061, 2017). "Moreover, studies have shown that reduction in LDHA expression in cancer cells either by genetic knock down (shRNA) or inhibitor (FX11) resulted in the shift to oxidative phosphorylation (OXPHOS) and increased intracellular ROS." (PMID 28525376, 2017). "LDHA was essential for maintaining glycolysis and improving the cancer cells’ invasive activity." (PMID 28749413, 2017). "Inhibition of LDHA has an anti-proliferative effect on cancer cells." (PMID 28915924, 2017). "LDHA has been implicated in the pathogenesis and progression of many cancer types and recent proteomic studies have also shown LDHB to be strikingly increased in cancer cells." (PMID 28086232, 2017). "Hif-1α has been shown to regulate LDHA expression in cancer cell lines." (PMID 29615570, 2017). "Moreover, studies have shown that reduction in lactate dehydrogenase A (LDHA) expression in cancer cells either by genetic knock down (shRNA) or inhibitor (FX11) resulted in the shift to oxidative phosphorylation (OXPHOS) and increased intracellular ROS." (PMID 28819582, 2017). "The over-expression of LDHA inevitably promotes the production of LDH by cancer cells." (PMID 28056913, 2017). "As we expected, isoflurane treatments significantly up-regulated both protein and mRNA expressions of HK2 and PKM2, whose overexpression in cancer cells resulted in up-regulated aerobic glycolysis and LDHA, which catalyzes the interconversion of pyruvate and L-lactate." (PMID 28951521, 2017). "Because PKM2 is an essential enzyme for regulation of aerobic glycolysis in cancer cells, we further determine that NEK2 expression is increased in high-risk patients and positively correlates with aerobic glycolysis genes including HK2, ENO1, and LDHA." (PMID 28086949, 2017). "The expression of LDHA was found to be increased in various types of human cancers, including PC." (PMID 28193910, 2017). "LDHA is over-expressed in several cancer types, including NSCLC." (PMID 29285267, 2017). "This could be achieved through the inhibition of LDHA, suggested to be a promising cancer therapeutic target due its role as the catalyst of the pyruvate conversion into lactate, which is subsequently released in the TME." (PMID 28969664, 2017). "As ROS plays an important role in radiation-induced cellular damage and cancer radioresistance, we investigated whether ROS is involved in the LDHA-siRNA and FX-11 mediated radiosensitization effects." (PMID 27708237, 2016). "As such, LDHA has been explored as a therapeutic target for cancer therapy." (PMID 27374086, 2016). "Another LDHA inhibitor, oxamate, re-sensitizes taxol-resistant cancer." (PMID 26918353, 2016). "Hif-1α is a well-known inducer of LDHA expression in many cancer cell lines." (PMID 27585295, 2016). "In some cancers LDHB can replace LDHA, hence limiting the efficacy of the LDHA inhibitors." (PMID 27455839, 2016). "Lactate dehydrogenase A (LDHA) is involved in a variety of cancers." (PMID 26902416, 2016). "Lactate dehydrogenase A (LDHA) is an enzyme that plays a vital role in metabolism in cancers." (PMID 27374173, 2016). "Likewise, most types of cancer cells display the Warburg effect with elevated glucose uptake and conversation to lactate mediated, amongst other factors, by overexpression of LDHA." (PMID 27144334, 2016). "Several miRNAs target LDHA and regulate glycolysis in cancer cells." (PMID 26918353, 2016). "Lactate dehydrogenase A (LDHA) is involved in various cancers." (PMID 27374173, 2016). "The role of LDHA in cancer malignancy has been intensively studied to date." (PMID 25973606, 2015).
cancer (continued). "Furthermore, we found that miR-34a, miR-34c, miR-369-3p, miR-374a, and miR-4524a/b target LDHA and regulate glycolysis in cancer cells." (PMID 26062441, 2015). "The modulation of the drug targets was examined under these varying oxygen conditions and of the five targets examined, PFKFB3 and PDHK1 were up-regulated under hypoxic conditions in both cancer cell lines, while Hexokinase II and LDHA were up-regulated only in MCDF-7 cells at 0.5% O2." (PMID 26259240, 2015). "Next, to detect whether LDHA has an implication for cancer progression, cell migration and invasion assays were performed." (PMID 25983002, 2015). "By contrast, the Taxol-resistant cancer cells showed elevated LDHA expression levels." (PMID 25789051, 2015). "Indeed, the upregulation and overexpression of LDHA is an important part of cancer metabolism, as knockdown affects cancer progression, proliferation, and survival." (PMID 24363178, 2014). "This renders LDHA a promising molecular target for the treatment of various cancers." (PMID 24466056, 2014). "Cancer cells often exhibit enhanced aerobic glycolysis, also known as the Warburg effect, with increased transcriptional regulation of a number of glycolytic enzymes including lactate dehydrogenase-A (LDH-A)." (PMID 24667972, 2014). "Further studies showed that alterations of LDHA expression lead to changes in cancer metabolism." (PMID 24884974, 2014). "We next investigated LDHA expression in other cell lines and in primary human cancer tissues." (PMID 24280423, 2013). "In addition, gene expression of both lactate dehydrogenase A and B was up-regulated in lal−/− bone marrow MDSCs, a pathway generally used by cancer cells (Warburg effect)." (PMID 22383970, 2012). "Among the potential molecular markers that could aid in diagnosis or prognosis of EmCa, some such as PKM2, LDHA and cathepsin B have already been explored for their therapeutic potential in other cancers." (PMID 21305022, 2011). "Potentially, HIF-1 may act in a manner similar to cancer cells by upregulating LDHA and PDK in Aβ resistant cells and surviving neurons of the AD brain." (PMID 21541279, 2011). "LDHA increase has been shown in a variety of cancers but the hypothesis that LDHA is involved in an apoptotic pathway could imply a more complex role of this enzyme in ccRCC." (PMID 17123452, 2006). "In contrast, as for pyruvate being a substrate, we observed an increase in lactate dehydrogenase (LDHA), which is known to be playing an active role in anaerobic glycolysis, thus reflecting the hypoxic conditions known to be present in proliferating cancer cells, especially RCC." (PMID 17123452, 2006). "Moreover, we discuss the therapeutic potential of targeting cancer metabolism, focusing on key enzymes involved in glycolysis, the pentose phosphate pathway, and amino acid metabolism, including lactate dehydrogenase A, hexokinase, phosphofructokinase and others." (PMID 40076506, 2025). "Targeting LDHA might serve as an effective and attractive strategy for cancer treatment." (PMID 39930542, 2025). "Therefore, while the cancer model provides a valuable mechanistic hypothesis, the specific nuclear signaling role of LDHA in cardiomyocytes warrants dedicated investigation." (PMID 40710803, 2025). "Additionally, LDHA phosphorylation and activation can promote cancer cell invasion and metastasis, making it a potential therapeutic target and prognostic marker for human cancers." (PMID 39759516, 2024). "Consequently, we discussed the association of LDHA expression with TMB and MSI in pan-cancer." (PMID 38709280, 2024). "In addition, LDHA can also serve as a biomarker for various malignant tumors." (PMID 38511143, 2024). "Thus, targeting dysregulated ncRNAs may be potential targets to suppress cancer development through regulating the expression of LDHA." (PMID 38238756, 2024).
cancer (continued). "It had been reported that CNEPE and LDHA could be targeted by miRNA in some cancers." (PMID 37925501, 2023). "In this regard, studying the modulatory effects of miRNAs and lncRNAs on those glycolytic proteins linked with cancer progression, e.g., HK1, GAPDH, PKM2, GLUT1, GLUT3, HIF-1α, CAV1, Ras, HK2, LDHA, PGI/AMF, and PFKFB3, might be very favorable for the design of novel treatments for PC." (PMID 36332600, 2023). "Therefore, targeting LDHA can create new opportunities to fight cancer cells." (PMID 37965333, 2023). "The so-called “Warburg effect”, which was first described in cancer cells and later identified in immune cells, comprises a metabolic switch from oxidative metabolism towards glycolysis without a hypoxic environment, namely aerobic glycolysis preference, which is dependent on LDHA induction." (PMID 37833292, 2023). "Lactate production and activity play an important role in maintaining cellular and biological functions as well as immune regulation, therefore, the realization of the anti-cancer potential of LDHA must overcome the non-targeting effects associated with LDHA blockade first." (PMID 37965331, 2023). "All these findings suggest that LDHA may be a possible target molecule for cancer treatment." (PMID 35525866, 2022). "Finally, it was shown that INSR and LDHA might be used as prognostic markers for developing premalignant lesions to cancer involving glucose metabolism in digestive diseases." (PMID 35755820, 2022). "In addition, we overexpressed LDHA in BxPC-3 and SW1990 cells to verified whether LDHA could overturn the anti-cancer effects of sh-LINC01128." (PMID 35193567, 2022). "Previous studies have shown that high expression of LDHA is involved in cell proliferation and survival, migration, invasion, angiogenesis, and immune evasion in cancer, indicating that LDHA may be a potential prognostic marker and therapeutic target in cancer." (PMID 36678382, 2022). "Therefore, LDHA expression or activity has become a valued target of cancer therapy." (PMID 36407005, 2022). "Reduced glycolysis and lactate production in sgSlc4a4 cancer cells likely reflects the inhibitory effect of a lower pHi on the activity of glycolytic enzymes including hexokinase, 6-phosphofructokinase and lactate dehydrogenase A (LDHA), the latter converting pyruvate into lactate." (PMID 36522548, 2022). "In addition to normal cell metabolism, LDHA acts as a promotor in cancer development." (PMID 36313570, 2022). "However, how methylation promotes LDHA function and whether this modification exists in other cancers remain a mystery." (PMID 36407005, 2022). "There is emerging evidence that suppression of LDHA may exert novel anti-oncogenic effects both by reducing the cellular metabolism and by functioning synergistically with other anti-cancer treatments, such as radiotherapy, cytotoxic chemotherapy, and cancer-targeted drugs." (PMID 36313570, 2022). "Recent studies showed that LDHA may be served as a therapeutic target of cancer immunotherapy." (PMID 34307169, 2021). "In addition, LDHA is highly expressed and facilitates chemoresistance in various cancers." (PMID 34540667, 2021). "Considering the importance of LDH in cancer metabolism and HO-1-mediated effects on this enzyme transcription and activity in PCa cells, we searched public database repositories and performed a bioinformatics analysis to determine the clinical significance of LDHA, LDHB and HMOX1." (PMID 34208670, 2021). "The important role of LDHA in maintaining a Warburg phenotype and promoting the tumorigenic potential of malignancies was confirmed by numerous findings showing that LDHA inhibition, gene silencing, or knockdown considerably decreased the tumorigenic potential in several types of cancer." (PMID 32365833, 2020). "Therefore, the oppression of LDHA can be a potential target for the treatment of cancer." (PMID 30886157, 2019). "Thus, LDHA affects initiation, maintenance, and progression of cancers." (PMID 31324019, 2019).
cancer (continued). "Thus, LDHA may be a potential target for cancer therapeutics due to the suppression of the lactate metabolism." (PMID 31324019, 2019). "Also miR-199a-3p can inhibit LDHA expression (by downregulating the Specificity protein 1 (Sp1)-transcription factor), which supports the critical contribution of a miR-199a-3p/Sp1/LDHA axis to aerobic glycolysis in cancer cells." (PMID 31035592, 2019). "In addition, c‐Myc and HIF‐1 could collaborate to activate LDHA transcription in various cancer cells." (PMID 30403008, 2018). "Second, LDHA may be involved in promoting cancer stem cells (CSCs) phenotype." (PMID 30403008, 2018). "Thus, targeting LDHA together with NAMPT may offer novel opportunities for selective killing of cancer cells, particularly in cancer types that are addicted to aerobic glycolysis for survival." (PMID 29541451, 2018). "LDHA expression and enzymatic activity were both increased in MDA RES, as well as in CEM RES, suggesting that LDHA activity may be not only a common mechanism of acquired resistance to NAMPT inhibition but also a new possible vulnerability of FK866-resistant cancer cells." (PMID 29541451, 2018). "Therefore, manipulation of LDHA expression may have impact on cancer cell proliferation, viability or invasiveness." (PMID 28193910, 2017). "Furthermore, HIF-1α has been demonstrated to act as a key regulator in glycolysis, HIF-1α is the best-known transcriptional regulators controlling expression of glycolysis genes, such as HK1, HK2, and LDHA, whose expression levels are highly elevated in cancer cells." (PMID 29137372, 2017). "Thus, dysregulated expression of ldha in our study could potentially accelerate progress in LDHA-targeted cancer therapy." (PMID 27158819, 2016). "Since mitochondrial dysfunction after radiation exposure may compromise energy supply and cell function, we focused on the expression of two metabolism-related genes, SLC2A1 and LDHA, which frequent overexpression by cancer cells contribute to increased glycolysis." (PMID 27513864, 2016). "Therefore, LDHA inhibition may restrict the energy supply in cancer cells, thereby decreasing their tumorigenicity." (PMID 26509967, 2015). "Similarly, we found high LDHA expression levels across primary human cancer tissues." (PMID 24280423, 2013). "However, low nanomolar inhibitors of the enzyme had EC50 no better than 400 nM when tested in cells, which could be explained by micromolar levels of LDHA found in the majority of cancer cell lines tested." (PMID 24280423, 2013). "Thus, targeting LDHA may be a promising therapeutic approach to treat cancers rich in LDHA, with presumed low systemic toxicity." (PMID 22859959, 2012). "Thus, the oxidation of pyruvate in the mitochondria supplies 30+ additional moles of ATP compared to its reduction to lactate via lactate dehydrogenase A (LDHA), which happens in case of insufficient oxygen levels or - in case of cancer cells - due to the Warburg effect." (PMID 22029671, 2011). "However, additionally, LDHA has recently been shown to have a critical role in the energy production of cancer cells through glycolysis, and maintaining this pathway may be a more important aspect of inhibition of PDH." (PMID 18542064, 2008). "Our findings reveal a novel regulatory axis where LDHA is activated by AKR1B10, highlighting critical enzyme–enzyme crosstalk in cancer metabolism." (PMID 41454479, 2026). "Considering the role of NF-κB in promoting tumors and regulating energy metabolism in cancer, we further demonstrated the function of YBX1 in glycolysis and RCC progression mediated by LDHA through lactic acid production and CCK-8 proliferation assays." (PMID 41507134, 2026). "Epigenetic changes dysregulate HIF-1α and metabolic enzymes like fructose-bisphosphatase FBP1, PKM, and Lactate dehydrogenase A (LDHA) in CAFs, fueling cancer growth." (PMID 40230452, 2025).
cancer (continued). "Our findings demonstrate that LDHA expression at both the protein and mRNA levels is significantly elevated in advanced-stage CRC compared with early-stage cancer tissues and adjacent normal tissues." (PMID 41368023, 2025). "Forkhead box protein M1 (FOXM1), a crucial transcriptional activator of LDHA and GLUT1, has potential effects on the glycolysis process in cancer." (PMID 39993964, 2025). "Analysis of mRNA expression in TCGA paired samples revealed notably enhanced levels of LDHA, SHC1 and CDKN3 in cancer tissues compared to adjacent tissues, whereas PCSK9, BTK, CAV2 and PDGFB showed significantly reduced expression." (PMID 40182622, 2025). "This STIP1‐mediated methylation and activation of LDHA by the AHCY‐PRMT3 complex leads to heightened glycolytic flux, meeting the bioenergetic and biosynthetic demands of rapid cancer cell proliferation." (PMID 41163796, 2025). "Eight proteins (C-reactive protein, AGRN, XPOT, LDHA, C1QC, ORM1, ANGPTL4, and prostaglandin D2 synthase [PTGDS]) exhibited a continuously upward or downward trend in three or more cancer types." (PMID 39884577, 2025). "This distinction highlights the dual role of the immune microenvironment in cancer, in which CXCL13 enhances immune surveillance, while LDHA contributes to immune evasion." (PMID 40260244, 2025). "Simultaneously, dexamethasone also inhibits LDHA to suppress glycolysis in HCC, contributing to its anti-cancer effects." (PMID 39980550, 2025). "Therefore, altered expression of LDHA may contribute to tumorigenesis and cancer progression." (PMID 39930542, 2025). "The regulation of HIF1α, LDHA, and PDK1 by the ZFAS1-STAT3 axis is a novel insight that can have significant implications for understanding and targeting cancer metabolism." (PMID 40697388, 2025). "Cancer cells upregulate glucose transporters (GLUT1/3) and glycolytic enzymes (e.g., HK2, LDHA) to fuel rapid proliferation, outcompeting immune cells for glucose in the nutrient-scarce TME." (PMID 40734168, 2025). "Several proteins involved in glycolysis, including glucose transporter 1 (GLUT1), hexokinase 2 (HK2), and lactate dehydrogenase A (LDHA), are overexpressed in cancers." (PMID 41392241, 2025). "On the contrary, increased protein and mRNA levels of LDHA, PGK1, and HK1 were detected in cancer cells cultured at different concentrations of NaLac." (PMID 40849487, 2025). "Through a comparative analysis, we identify consistent upregulation of glycolytic enzymes such as LDHA, PKM2, and HK2, as well as nutrient transporters like GLUT1, ASCT2, and LAT1, which contribute to cancer progression, metastasis, and therapy resistance." (PMID 41154605, 2025). "miR‐5586‐5p also suppresses the expression of glycolytic genes, lactate dehydrogenase A (LDHA), hexokinase 2 (HK2), phosphoglycerate kinase 1 (PGK1), and solute carrier family 2 member 1 (SLC2A1), thereby suppressing glycolysis and cancer progression." (PMID 40448344, 2025). "By upregulating molecules involved in glycolysis, such as GLUT1, LDHA and HK2, HIF‐1α enhances glucose uptake and lactate production, providing cancer cells with energy and biosynthetic precursors essential for rapid growth and survival." (PMID 39993964, 2025). "UCHL3 promotes LDHA expression and can be reduced by shFOXM1, and low-expression of LDHA partially reversed the inhibition of aerobic glycolysis induced by overexpression of UCHL3, UCHL3 may be a potential diagnostic and therapeutic target for the treatment of cancer." (PMID 40630951, 2025). "Collectively, cancer cells increase glycolysis by upregulating metabolic enzymes, such as HK2, PKM2, and LDHA, to sustain proliferation and survival." (PMID 40734168, 2025). "In the targeted therapy of cancer, regulators such as hexokinase 2 (HK2), pyruvate kinase M2 (PKM2), enolase 1 (ENO1), and lactate dehydrogenase A (LDHA) are crucial for the glycolytic pathway." (PMID 39484162, 2024).